EPO (erythropoietin)
Diseases named in the same sentence as EPO in open-access papers (continued):
Sharing a sentence is not in itself a finding about the gene and the disease.
polycythemia (continued). "Unlike SLC30A10 deficiency, SLC39A14 deficiency does not produce liver dysfunction, polycythemia, or EPO excess)." (PMID 38652538, 2024). "Unlike SLC30A10 deficiency, SLC39A14 deficiency does not produce liver disease, polycythemia, or EPO excess." (PMID 38652538, 2024). "A 57-year-old Japanese man presented with polycythemia and an elevated erythropoietin level." (PMID 36890599, 2023). "Thus, it can be concluded that EPO levels cannot be utilized for a definitive diagnosis of reactive erythrocytosis." (PMID 35775283, 2023). "We first studied EPO levels, which have been reported to be increased in reactive erythrocytosis." (PMID 35775283, 2023). "Primary and secondary polycythemia can be differentiated by the level of EPO." (PMID 35805729, 2022). "In patients with Pacak–Zhuang syndrome, the pathologic accumulation of HIF2α and subsequent transcriptional upregulation of HREs manifests as polycythemia with inappropriately elevated EPO, hypertension, and functional norepinephrine-secreting paragangliomas during early adolescence." (PMID 36358730, 2022). "A low EPO level (2.9 mU/mL) has a specificity of 92% and sensitivity of 64% for the diagnosis of polycythemia vera; on the contrary, a high EPO level (>15.1 mU/mL) has a specificity of 98% and a sensitivity of 47% for the diagnosis of secondary polycythemia in a cohort study of 125 patients." (PMID 35805729, 2022). "For example, the discovery and investigation of another homozygous variant, p.D126N in exon 2, in one pediatric patient with early onset pulmonary hypertension, polycythemia, and multiple hepatic hemangiomas, also indicated only mild EPO hypersensitivity of erythroid progenitors." (PMID 35205407, 2022). "Through association analysis, we show that male patients presenting with idiopathic erythrocytosis, and normal EPO levels could be the best candidates for the search for the JAK2 GGCC_46/1 haplotype and CALR rs1049481_G allele." (PMID 36031623, 2022). "Polycythemia and hyperbilirubinemia are considered as a counter-regulatory mechanism of this relative hypoxic state, which triggers the secretion of erythropoietin (EPO) and increases the production of red blood cells." (PMID 36216857, 2022). "TEMPI (telangiectasias, elevated erythropoietin level and erythrocytosis, monoclonal gammopathy, perinephric fluid collections, and intrapulmonary shunting) syndrome is a rare and newly defined multisystemic disease, which belongs to “monoclonal gammopathy of clinical significances”." (PMID 35663307, 2022). "Despite extensive investigations including EPO level, which was normal; stem cell cultures; bone marrow examination; erythrocyte and plasma volume measurement, which showed absolute erythrocytosis, no cause for erythrocytosis was identified." (PMID 34946900, 2021). "Patients with idiopathic erythrocytosis are directed to targeted genetic testing including nine genes involved in oxygen sensing pathway in kidneys, erythropoietin signal transduction in pre-erythrocytes and hemoglobin-oxygen affinity regulation in mature erythrocytes." (PMID 34440324, 2021). "In rare instances, SH2B3/LNK exon 2 mutations or polymorphisms have been reported in patients with unexplained erythrocytosis, with subnormal serum EPO levels, and absence of JAK2, MPL, and EPOR mutations." (PMID 34021251, 2021). "Four types of erythrocytosis are known to be caused by mutations in genes encoding key players of oxygen-sensing signaling, namely VHL (ECYT2), EGLN1/PHD2 (ECYT3), EPAS1/HIF2α (ECYT4) and EPO (ECYT5)." (PMID 34440324, 2021). "Here, the short course of EPO did not cause polycythemia, a possible EPO adverse effect in sepsis, in all of these models." (PMID 34831360, 2021). "In addition, in a five-generation kindred with erythrocytosis, a novel heterozygous 5′UTR EPO variant has been newly discovered; the mutated 5′UTR of EPO augments interaction with HIF2, leading to increased production of EPO." (PMID 34021251, 2021).
polycythemia (continued). "An extensive study of one family with idiopathic erythrocytosis indicated, that transcription of EPO mRNA from an alternative promoter, due to the frameshift mutation in exon 2 that interrupts translation of the main EPO mRNA, can lead to excess production of erythropoietin and erythrocytosis." (PMID 34440324, 2021). "To investigate whether two EPO regimens lead to the obvious erythrocytosis, we checked red blood cell (RBC) count of four groups." (PMID 31929736, 2020). "Moreover, tubular VEGF-A deletion resulted in pronounced polycythemia due to elevated erythropoietin (EPO) production, suggesting that PTC loss induces tissue hypoxia and thereby stimulates renal EPO producing cells." (PMID 33158122, 2020). "No subclinical hypoxia was detected by repeated blood gas analyses, and the fact that excessive EPO production was only observed in the patient who developed symptomatic erythrocytosis might suggest it was related to the onset of renal cysts." (PMID 32546701, 2020). "Modulation of endogenous EPO signaling in mice with Von Hippel–Lindau (VHL) mutation in osteoblasts caused an increase in hypoxia inducible factor-1/2 (HIF), resulting in elevated EPO production in osteoblasts and polycythemia." (PMID 33330462, 2020). "Secondary polycythemia occurs as a consequence of elevated circulating erythropoietin (EPO), while primary polycythemia is due to intrinsic factors (e.g., somatic JAK2V617F mutation and hereditary dominant EPOR mutations) of erythroid progenitors in the bone marrow and is EPO-independent." (PMID 31091718, 2019). "Elevated plasma EPO confirmed secondary polycythemia in the syndrome patients, but it is still unclear whether primary polycythemia exists." (PMID 31091718, 2019). "We thus investigated an alternative mechanism causing polycythemia not responsive to EPO level reduction with transient treatment." (PMID 31091718, 2019). "However, polycythemia persisted after PT2385 treatment, suggesting an alternative erythropoietin-independent mechanism of polycythemia." (PMID 31091718, 2019). "Accordingly, HIF2A-mutated PHEO/PGLs show increased expression of hypoxia-related genes such as EPO, EDN1 and VEGFA, which may be linked to polycythemia and oncogenesis." (PMID 30925729, 2019). "These two patients presented with multiple recurrent PPGL, polycythemia with normal or mildly elevated EPO, and were negative for HIF2A mutation." (PMID 30538672, 2018). "In addtion, erythrocytosis may be secondary to abnormal ventilation, which in turn stimulates the production of excess erythropoietin." (PMID 29156832, 2017). "Thus, in Irp1-/- mice, Irp1 deficiency derepresses HIF2α translation, which transcriptionally increases EPO expression and subsequently drives red blood production, leading to polycythemia as a consequence." (PMID 24982634, 2014). "Meanwhile, tumour cells stimulate the biosynthesis of hormone like substances, such as IGF-II, parathyroid hormone-related protein (PTHrP), and erythropoietin, which leads to the expression of paraneoplastic syndromes such as hypoglycaemia, hypocalcaemia, and erythrocytosis." (PMID 25525545, 2014). "Previous clinical reports have recorded erythrocytosis and an increase in EPO serum levels in patients with hepatocellular carcinoma, whereas histological evidences of augmented EPO synthesis have been identified from the analysis of hepatic cancer samples and liver tissue surrounding the tumor." (PMID 23052842, 2013). "Several medications, including recombinant erythropoietin and androgens, may result in erythrocytosis." (PMID 24312736, 2013). "Five-week treatment with total flavonoids of seabuckthorn improved hemodynamic, hematologic parameters, and erythropoietin content, which indicates that it is useful in the prevention of cobalt chloride- and hypobaric chamber-induced high-altitude polycythemia in rats." (PMID 23023684, 2012).
polycythemia (continued). "According to this concept, hypoxia stimulates erythropoietin production and erythropoiesis; the resulting polycythemia increases the O2-carrying capacity and O2 content of blood, and this improves tissue oxygenation and turns off further production of erythropoietin." (PMID 23023684, 2012). "MRLB-11055 effectively prevented EPO-induced STAT5 activation in the peripheral blood of acutely dosed mice, and could prevent EPO-induced splenomegaly and erythrocytosis in chronically dosed mice." (PMID 22623993, 2012). "However, In two different studies, healthy cynomologous macaques treated with macaque-derived EPO-expressing AAV vectors developed supraphysiologic levels of EPO and polycythemia." (PMID 23028782, 2012). "Consequently, the typical signs of HAPC develop as follows: profound arterial hypoxemia, persistent production of erythropoietin, and then extraordinary polycythemia." (PMID 23023684, 2012). "First, as compared with the relative low dose of EPO adopted in our study, a very high EPO dosage used in that clinical trial may raise other unidentified confounding effects such as a polycythemia and thrombosis event, thereby influencing patient outcomes." (PMID 21269484, 2011). "If EPO and EPO-R levels are negative, the patient would need to be worked-up for other secondary causes of polycythemia and consideration given to continued medical treatment for polycythemia vera after surgery." (PMID 19946506, 2009). "High EPO levels might be seen in both primary and secondary polycythemias." (PMID 39421127, 2024). "We believe there is a need for further studies that examine the diagnostic improvement obtained by employing the SII (and other inflammation indices) together with EPO measurements in patients with polycythemia, which could prove crucial for early or easier diagnosis of PV." (PMID 38793053, 2024). "However, given that Slc39a14 deficiency also impacted Mn levels in extrahepatic tissues, we could not formally exclude a role for SLC39A14 in those other tissues in determining EPO excess and polycythemia." (PMID 38652538, 2024). "Besides subcutaneous and intravenous administration of EPO, intravitreal injection may be more effective and have less systemic side effects such as hypertension, cardiovascular complications, and polycythemia." (PMID 36873065, 2023). "Nevertheless, some clinical signs could be related to RCC, such as polycythemia, hypercalcemia, hypertension, and Cushing’s syndrome, correlated to erythropoietin, parathyroid-related hormone, renin, and adrenocorticotropic hormone (ACTH) overproduction by cancer, respectively." (PMID 37372161, 2023). "It is important to notice that these events are not solely limited to oncology patients because erythropoietin‐stimulating agents have been associated with polycythemia, hypertension, thrombocytosis, platelet hyperactivity, and activation of blood coagulation, all of which are thrombogenic." (PMID 36314077, 2023). "Secondary polycythemia is a heterogeneous group of disorders characterized by an elevated red blood cell mass due to either a physiologically appropriate response to tissue hypoxia or physiologically inappropriate secretion of erythropoietin (EPO) and/or other contributing factors." (PMID 35805729, 2022). "Despite extensive investigations including EPO level, which was normal, stem cell cultures, bone marrow examination, and erythrocyte and plasma volume measurement, which showed absolute erythrocytosis and polysomnography, no cause for erythrocytosis was identified." (PMID 34946900, 2021). "An extremely large amount of EPO may be required to manifest polycythemia." (PMID 25295086, 2014). "EPO production by RCC cells and cyst epithelial cells in the left kidney may cause polycythemia." (PMID 25295086, 2014). "Indeed, the level of EPO or EPO-R in the reported case was not elevated, which helped exclude secondary causes of erythrocytosis." (PMID 19946506, 2009).
polycythemia (continued). "The hyperinsulinemic environment of macrosomic infants drives an increased oxygen demand, triggering erythropoietin (EPO) secretion and resulting in polycythemia." (PMID 40141785, 2025). "Erythrocytosis is a class-wide effect of TRT, mediated through stimulation of erythropoietin, suppression of hepcidin, and enhanced iron absorption." (PMID 41562957, 2025). "Among patients who developed erythrocytosis while using SGLT-2 inhibitors, hematology consultations occurred in 18 (1.6%) patients, with median serum erythropoietin (EPO) levels of 12.5 mIU/mL (range 7.1–17.61 mIU/mL, reference 2.59–18.50 mIU/mL)." (PMID 40640769, 2025). "They concluded that polycythemia was secondary to the release of EPO by malignant clones in response to anti-VEGF therapy, considering that RCC cells can synthesize EPO." (PMID 39165680, 2024). "For example, EPO has a short half-life (t1/2~5.6 h), and its affinity for EPOR2 is much higher than its affinity for EPOR/BcR; thus, side effects, such as polycythemia and thrombosis, can occur." (PMID 36769310, 2023). "Polycythemia is also observed when HIF-P4H-2 is inactivated in the FoxD1 lineage (24 and this study), as the erythropoietin-producing kidney tubular interstitial fibroblasts are also derived from the FoxD1 lineage." (PMID 35247391, 2022). "The secondary polycythemia displayed in the mice relates to a clinical condition, where an increase in RBC mass is seen together with increased serum EPO concentration." (PMID 34354145, 2021). "Recent research suggests Echinacea induced erythrocythemia and VO2 max results in an increase in serum erythropoietin (EPO)." (PMID 24967264, 2014). "Hypercalcemia as well as polycythemia are frequently observed in RCC patients and EPO produced by tumor cells raises the level of blood stem cells that preferentially colonize within highly vascularized RCC." (PMID 24520308, 2014). "Although the serum EPO (sEPO) level is reportedly elevated in 33–38% of patients with RCC, it is relatively rare that patients with RCC manifest polycythemia." (PMID 25295086, 2014). "Likewise, high EPO (>16.9 mU/mL) had high specificity (1.0; 95% CI 0.89–1.0) but low sensitivity (0.16; 95% CI, 0.11–0.21) for JAK2-negative (secondary) erythrocytosis." (PMID 40806795, 2025). "Low EPO (<3.8 mU/mL) had a Sn of 0.77 (95% CI, 0.62–0.87), Sp of 0.98 (95% CI, 0.94–0.99), −LR of 0.23 (95% CI, 0.13–0.41), and +LR of 33 (95% CI, 12.5–89.6) for the diagnosis of JAK2 mutant erythrocytosis." (PMID 40806795, 2025). "A positive EPO-JAKPOT score had a Sn of 0.95 (95% CI, 0.83–0.98), Sp of 0.66 (95% CI, 0.58–0.72), −LR of 0.07 (95% CI, 0.02–0.30), and +LR of 2.7 (95% CI, 2.2–3.4) to diagnose JAK2 mutant erythrocytosis." (PMID 40806795, 2025). "When polycythemia is observed in patients with SCLC, clinicians should consider not only the possibility of hypoxia or hematologic disorders but also evaluate for recurrence, metastasis, and the potential for ectopic EPO production." (PMID 40502212, 2025). "The classical EPO molecule is unlikely to be suitable for clinical application due to its erythropoietic side effects, including polycythemia, thrombotic events, and hypertension." (PMID 40697664, 2025). "In summary, the EPO-JAKPOT score shows potential for excluding JAK2 mutant erythrocytosis in select patients without molecular testing." (PMID 40806795, 2025). "Our case adds to the limited body of evidence on hydronephrosis-induced polycythemia and supports the notion that elevated EPO levels are not a universal finding." (PMID 39767963, 2024). "This case underscores the importance of considering renal pathologies, such as hydronephrosis, in the differential diagnosis of pediatric polycythemia, even in the absence of elevated serum EPO levels." (PMID 39767963, 2024). "Renal abnormalities should be considered in the differential diagnosis of pediatric patients with polycythemia, even in the absence of elevation of erythropoietin." (PMID 39767963, 2024).
polycythemia (continued). "It appears erythrocytosis may be a response to the development of microcytosis and that the changes in cell size and RBC count may result from the action of both hepcidin and erythropoietin." (PMID 39518858, 2024). "This case demonstrates a potential link between hydronephrosis and polycythemia, suggesting that hydronephrosis can induce polycythemia even in the absence of elevated serum erythropoietin levels." (PMID 39767963, 2024). "Only Hb, hematocrit, and PCV values were considered in our study to rule out polycythemia because of the lack of facility in our settings; however, it would be preferable to assess serum erythropoietin and red cell mass as well." (PMID 37208878, 2023). "Subsequently, blood properties are altered in response to hypoxia: one is to undergo in succession dehydration-induced plasma volume reduction, erythropoietin (EPO) secretion increase, polycythemia and eventually an elevated hemoglobin concentration, hence blood viscosity rising." (PMID 36061757, 2022). "EPO treatment induced palmar erythema and polycythemia, but did not impact blood leukocyte and platelet counts." (PMID 36329047, 2022). "In parallel, it was reported in an experimental study that losartan, an AT-II type 1 receptor (AT-1) antagonist, developed posttransplant erythrocytosis without altering serum erythropoietin levels." (PMID 34519192, 2021). "HIF2α also contains an IRE sequence and it has been reported that the expression of HIF2α mRNA is exclusively regulated by IRP1, as IRP1-/- but not IRP2-/- mice developed erythrocytosis due to increased expression of EPO." (PMID 34440324, 2021). "Despite the concerns on EPO-induced thrombotic events, thrombotic vascular events were not increased in the present study, perhaps due to the non-polycythemia in our patients." (PMID 34831360, 2021). "Additionally, axitinib can induce polycythemia and other RBC dysfunction in patients with ccRCC due to complex interactions between hypoxia inducible factor 1 alpha (HIF-1a), VEGF and EPO." (PMID 33602288, 2021). "However, other studies observed reduction in bone volume but without an increase in osteoclast activity in C57BL/6 mice given exogenous EPO or in C57BL/6 mice transplanted with bone marrow from Tg6-mice to induce polycythemia." (PMID 33330462, 2020). "The suppression of erythropoietin stimulation by posttransfusion polycythemia did not inhibit the erythroid program in LK cells in regenerating hematopoiesis, nor did it suppress the enhanced expression of CD71." (PMID 32258026, 2020). "The most common erythropoietin (EPO)-dependent etiologies of erythrocytosis include malignancies, chronic hypoxia and obstructive sleep apnea, while myeloproliferative disorders account for most cases of EPO-independent erythrocytosis." (PMID 31266452, 2019). "Although polycythemia is a common peripheral blood observation in RCC patients, the exact pathogenesis of EMH within RCC is not known; it has been previously reported that 74% of RCCs show EPO immunohistochemically." (PMID 24520308, 2014). "Notably, mutant mice lacking VHL in cells of the osteoblast lineage develop severe polycythemia, which is due to HIF-2α dependent overproduction of erythropoietin (EPO) by osteoblasts." (PMID 23847596, 2013). "The hematologists’ diagnosis was secondary polycythemia due to heavy smoking (smokers’ polycythemia) because the white blood cell and platelet counts were within normal limits and the erythropoietin was not increased." (PMID 23374961, 2013). "As analyzed for the polycythemia- associated EPOR allele EPOR-T-392, an additional observation was an apparent lack of any major EPO- refractive EPOR-T species (i.e., potentially corresponding to an intracellular pool)." (PMID 22253704, 2012). "Despite the implication of increased erythropoietin levels in the pathogenesis of erythrocytosis, erythropoietin level was found to be normal in two of these reports while the erythropoietin levels were not measured in other two." (PMID 22834973, 2012).